MMP2 (matrix metallopeptidase 2)
Diseases named in the same sentence as MMP2 in open-access papers (continued):
Sharing a sentence is not in itself a finding about the gene and the disease.
uterine sarcoma (2 papers, 2023 to 2024). "However, there are limited data supporting the association between TEM1 and MMP-2 and their roles in uterine sarcoma." (PMID 36639546, 2023). "In order to investigate the involvement of tumor endothelial marker 1 (TEM1) and matrix metalloproteinase 2 (MMP-2) in the development of uterine sarcoma, immunohistochemistry analysis is also used." (PMID 38410101, 2024). "The in vivo data validated the role of TEM1 in regulating MMP-2 and promoting metastasis in uterine sarcoma." (PMID 36639546, 2023). "TEM1 promoted uterine sarcoma migration and invasion via increasing MMP-2 activity and ECM remodeling/degradation." (PMID 36639546, 2023). "TEM1 and MMP-2 were highly expressed in all 17 of high stage (III-IV) uterine sarcoma specimens and 62.5% or 5 of 8 of low-grade specimens." (PMID 36639546, 2023). "By establishing TEM1 overexpression and knockdown MES-SA cell models, we demonstrated that TEM1 regulated the expression of MMP-2 and promoted the invasion and migration of uterine sarcoma cells through ECM remodeling." (PMID 36639546, 2023). "The results confirmed the role of MMP-2 in promoting the uterine sarcoma progress." (PMID 36639546, 2023). "TEM1 and MMP-2 were highly expressed in all 17 of high stage (III-IV) uterine sarcoma specimens." (PMID 36639546, 2023). "TEM1 promoted uterine sarcoma progression by regulating MMP-2 activity and ECM remodeling." (PMID 36639546, 2023). "Additionally, by influencing MMP-2 production and extracellular matrix (ECM) remodeling, TEM1 accelerates the development of uterine sarcomas." (PMID 38410101, 2024). "Consistent with our previous work in which we found that TEM1 was overexpressed in uterine sarcoma specimens and promoted the migration and invasion of uterine sarcoma MES-SA cells, our present data showed that TEM1 expression level was correlated with tumor stage and MMP-2 expression." (PMID 36639546, 2023).
Vertigo (2 papers, 2019 to 2020). An abnormal sensation of spinning while the body is actually stationary. "However, in the current study, MMP-2, -3 or -9 levels were not higher in vertigo patients with LI or advanced stages of WMH, whereas the TIMP-1 level was higher in vertigo patients with higher WMH grades (grade 2 and 3)." (PMID 31474817, 2019).
Zinc deficiency (2 papers, 2025). A deficiency of the essential metal Zinc; an essential cofactor for many enzymes. "Our qPCR results demonstrate a significant increase in mRNA expression levels of TIMP-1 and PAI-1 under zinc deficiency condition, while the expression of MMP-2 decreased." (PMID 39028478, 2025).
acute conjunctivitis (1 paper, 2013). Acute inflammation of the conjunctiva. "In conclusion, we have examined the effects of azithromycin on the LPS-induced acute conjunctivitis model in rats, and we found evidence that topical azithromycin inhibits the expression of inflammatory cytokines such as IL-6, MMP-2 activity, and NF-κB." (PMID 23378729, 2013).
acute leukemia (1 paper, 2011). A clonal (malignant) hematopoietic disorder with an acute onset, affecting the bone marrow and the peripheral blood. "Our findings suggest that the degradation of tight junction proteins ZO-1, claudin-5 and occludin by MMP-2 and -9 secreted by leukemic cells constitutes an important mechanism in the BBB breakdown which contributes to the invasion of leukemic cells to the CNS in acute leukemia." (PMID 21857898, 2011).
acute monocytic leukemia (1 paper, 2012). Acute monoblastic leukemia (AML-M5), is one of the most common subtypes of acute myeloid leukemia (AML) that is either comprised of more than 80% of monoblasts (AML-M5a) or 30-80% monoblasts with (pro)monocytic differentiation (AML-M5b). "Consistent with our data, it was reported that inhibition of MMP-2 and MT1-MMP by siRNA substantially impairs the migration of a highly invasive human acute monocytic leukemia cell line SHI-1." (PMID 24213464, 2012).
adhesive capsulitis (1 paper, 2024). "It was demonstrated that the mRNA expression of MMP-2 in samples from patients with adhesive capsulitis was found more often than MMP-1 or MMP-3." (PMID 38381214, 2024).
aging (1 paper, 2019). A developmental process that is a deterioration and loss of function over time. "As MMPs are known to cause skin aging through the degradation of collagen, we also examined the activity of MMP-1 and the expression levels of MMP-1, MMP-2, and MMP-9." (PMID 30669248, 2019).
Alport syndrome (1 paper, 2017). A rare renal disease characterized by glomerular nephropathy with hematuria progressing to end-stage renal disease (ESRD), frequently associated with sensorineural deafness, and occasionally with ocular anomalies. "Expression of MMPs occurs with disease progression in Alport syndrome and MMP-2, MMP-9, and MMP-12 have been linked to GBM alterations." (PMID 29167507, 2017).
amblyopia (1 paper, 2019). Decreased vision that results from abnormal visual development. "The homeostatic regulation of the threshold for activity-dependent activation of MMP2/9 at thalamo-cortical synapses allows recruitment of this pathway by vision compromised by amblyopia." (PMID 31868167, 2019).
ampullary cancers (1 paper, 1996). "The results implicate MMP2, MMP3 and TIMP1 in the invasive phenotype of pancreatic and ampullary cancer." (PMID 8611434, 1996).
anaplastic carcinoma (1 paper, 2020). "More interestingly, they also observed MMP-2-positive expression in tumor cells and/or the adjacent tissue in all anaplastic carcinoma (ATC) cases, and the cytological atypia of cells with BSG positive expression was greater than that in cells with negative BSG expression." (PMID 32891152, 2020).
ankylosing spondylitis (1 paper, 2019). An autoimmune chronic inflammatory disorder characterized by inflammation in the vertebral joints of the spine and sacroiliac joints. "Silencing of MMP-2 gene reduced the DNA damage in HDFs, and protected cardiomyocyte from ischemia-reperfusion injury and reduced the osteogenic transformation of fibroblasts by inhibiting the SMP/Smad pathway in ankylosing spondylitis." (PMID 31367263, 2019).
anterior subcapsular cataracts (1 paper, 2013). "For example, using a TGFβ-induced model of anterior subcapsular cataracts in rats, we demonstrated that cotreatment with the MMP-2/9 specific inhibitor effectively prevented anterior subcapsular cataract formation and the associated deposition of matrix." (PMID 23559862, 2013).
anxiety disorder (1 paper, 2024). A category of psychiatric disorders which are characterized by anxious feelings or fear often accompanied by physical symptoms associated with anxiety. "In individuals with current depressive or anxiety disorders compared to healthy controls, elevated levels were observed in CRP, IL-6, IL-8, IL-18, MCP-1, MIP-1α, MIP-1β, MMP2, and TNF-β, while TNF-α, IL-10, IFN-γ, IL-2, and IL-4 levels either showed no significant elevation or were lower." (PMID 39273641, 2024).
Aortic root aneurysm (1 paper, 2016). An abnormal localized widening (dilatation) of the aortic root. "We also identified active MMP-2 in all tissue samples from patients with ascending aortic/aortic root aneurysms." (PMID 27802285, 2016). "ELISA results revealed, that serum MMP-2 levels were higher in control subjects (mean 240.3 +/- 46.4) than in patients with ascending aortic and aortic root aneurysms (mean = 190.3 +/- 48.3) with P = 0.0014 for both differences." (PMID 27802285, 2016). "Pro-MMP-2 was detected in all tissue and serum samples from patients with ascending aortic/aortic root aneurysms, irrespective of valve morphology or other clinical parameters and in serum from healthy controls." (PMID 27802285, 2016).
aortitis (1 paper, 2025). Inflammation of the aorta. "In the atheromatous plaque stage, SMS2 overexpression significantly upregulates the expression of aortic matrix metalloproteinase-2 (MMP-2), monocyte (MCP-1, tissue factor (TF), and cyclooxygenase-2 (COX-2) biomarkers of aortitis." (PMID 39920588, 2025).
arteriosclerosis (1 paper, 2016). A vascular disorder characterized by thickening and hardening of the walls of the arteries. "The matrix metalloproteinases (MMP)-2 and −9 were shown to promote these VSMC calcifications and their inhibition is of therapeutic value to prevent arteriosclerosis in preclinical studies." (PMID 27716072, 2016).
arteritis (1 paper, 2023). An inflammatory process affecting an artery. "Due to the severe arteritis occurring with SRMA and due to an upregulation of metalloproteinases (MMPs), including MMP-2 and -9, a disruption of the blood–brain barrier occurs." (PMID 37627467, 2023).
autoimmune thyroiditis (1 paper, 2019). "In summary, our results suggest that decreased invasiveness of embryonic trophoblasts in autoimmune thyroiditis is associated with down-regulation of PD-1/PD-L1 signaling pathway and inhibition of MMP-2 and MMP-9 expression." (PMID 31656199, 2019). "Thus, we infer that, in the placenta of pregnant mice with autoimmune thyroiditis, attenuation of the PD-1/PD-L1 signaling pathway may inhibit p-ERK1/2 signaling and its downstream effects on MMP-2 and MMP-9." (PMID 31656199, 2019).
autosomal dominant cutis laxa (1 paper, 2023). Autosomal dominant cutis laxa (ADCL) is a connective tissue disorder characterized by wrinkled, redundant and sagging inelastic skin associated in some cases with internal organ involvement. "Similarly, in a study of 8 autosomal dominant cutis laxa patients, serum MMP-2 and 9 were significantly upregulated compared to normal levels suggesting systemic elastin degradation in autosomal dominant cutis laxa is due to protease dysregulation." (PMID 37001705, 2023).
Azoospermia (1 paper, 2018). Absence of any measurable level of sperm,whereby spermatozoa cannot be observed even after centrifugation of the semen pellet. "A previous study has shown that MMP-2 strongly affects the sperm count and also the level of MMP-2 is higher in normozoospermia rather than azoospermia." (PMID 30167394, 2018).
bacterial meningitis (1 paper, 2018). Inflammation of the membranes surrounding the brain and spinal cord due to a bacterial infection. "There are no previous reports about the relationship between levels of CSF MMP-2 and bacterial meningitis." (PMID 29479521, 2018). "However, previous reports show that increased levels of serum MMP-2 may reflect the degree of damage to the BCB in bacterial meningitis." (PMID 29479521, 2018).
Bowen’s disease (1 paper, 2025). "Those biochemical observations may explain the reduced expression of MMP-2 in keratoacanthoma lesions and Bowen’s disease." (PMID 40724562, 2025).
Brain atrophy (1 paper, 2025). Partial or complete wasting (loss) of brain tissue that was once present. "Together with MMP-9, MMP-2 appears to promote and fine-tune neuroinflammatory processes such as the expression of chemokines and pro-inflammatory cytokines, and large increases in MMP-2 over time have been associated with enhanced brain atrophy." (PMID 40869114, 2025).
brain inflammation (1 paper, 2017). "Interestingly, MMP-2 has already been associated to brain inflammation in canine VL48, but it may also play a role in the control of inflammation, specially by cleaving CCL-749, which is concomitantly increased in the brain of infected mice." (PMID 28814754, 2017).
breast disease (1 paper, 2009). "Somiari and coworkers have suggested that circulating MMP-2 and MMP-9 levels are associated with disease severity and may permit the classification of patients with breast disease." (PMID 19889214, 2009).
bruxism (1 paper, 2020). Excessive clenching of the jaw and grinding of the teeth. "Our hypothesis was that MMP2, MMP9, and/or COMT associate with bruxism, and that variation in these genes may be biomarkers of the risk of developing the condition." (PMID 32471213, 2020).
buccal mucosa cancer (1 paper, 2013). "RT-PCR and western blot analyses were conducted to determine whether metastasis in the buccal mucosa cancer model was a result of gene regulation of metastatic mediators, specifically MMPs (MMP-2 and MMP-9) and TIMPs (TIMP-1 and TIMP-2)." (PMID 23599733, 2013).
calcification (1 paper, 2017). Process by which organic tissue becomes hardened by the physiologic deposit of calcium salts. "Our results indicated that miR-29b-3p is involved in the progression of pathological vascular calcification by targeting MMP2." (PMID 28164126, 2017).
cardiac arrest (1 paper, 2022). Cessation of breathing and/or cardiac function. "Our results are consistent with previous data showing that MMP-2 (more than MMP-9) plays a critical role in BBB disruption, glial cell activation, and white matter damages after chronic cerebral hypoperfusion in animal models and patients with cardiac arrest." (PMID 36010557, 2022).
central obesity (1 paper, 2022). "Interestingly this MMP-2 rs 243,865 SNP has been associated with central obesity and non-alcoholic fat liver disease and with increased risk of cirrhotic hepatopulmonary syndrome in Chinese patients." (PMID 35264591, 2022).
cerebral microbleeds (1 paper, 2023). Cerebral microbleeds are a group of pathological processes affecting the small arteries, arterioles, capillaries and venules of the brain, as detected by brain imaging techniques. "At multivariate logistic regression analysis adjusted for age, sex, CHA2DS2-VASc, HAS-BLED and type of anticoagulant, matrix metalloproteinases (MMP)-2 levels were significantly and positively associated with the presence of cerebral microbleeds (CMBs)." (PMID 37959331, 2023).
cerebral palsy (1 paper, 2025). A group of disorders affecting the development of movement and posture, often accompanied by disturbances of sensation, perception, cognition, and behavior. "A significant difference was found in the frequencies of the ATG and GCT haplotypes of the MMP2 gene polymorphisms when comparing patients with cerebral palsy to those without." (PMID 41464177, 2025).
cervical disease (1 paper, 2014). "With respect to cervical disease, the metastatic potential of CIN has been correlated to the expression of three proteins including matrix metalloproteinase-2 (MMP-2), MMP-9, and urokinase-type plasminogen activator." (PMID 24416269, 2014).
chordoma (1 paper, 2020). Chordomas are rare malignant tumors arising from embryonic remnants of the notochord in axial skeleton. "Our previous observations suggested that miR-140-3p, miR-1237-3p, and miR-574-3p could control biological behavior of chordoma cells possibly by modulating receptor tyrosine kinase pathways and expression of MMP2 and PD-L1, respectively." (PMID 33194623, 2020).
chronic bronchitis (1 paper, 2014). A type of chronic obstructive pulmonary disease characterized by chronic inflammation in the bronchial tree that results in edema, mucus production, obstruction, and reduced airflow to and from the lung alveoli. "MMP-2 level at T18 was associated with body mass index (p < 0.01, 95% CI [0.25;0.93]) but not with age, smoking history, dyspnea, chronic bronchitis and the number of exacerbation in the past year." (PMID 25427655, 2014).
Chronic colitis (1 paper, 2021). A chronic inflammatory disease of the large intestine (colon, cecum and rectum). "We used qRT-PCR analysis to test the expression of MMPs known to be regulated in CD and showed that MMP-9 and MMP-2 were upregulated, but TIMP-1 was downregulated after the TFA treatment in the TNBS-induced chronic colitis mice model." (PMID 35002710, 2021).
chronic inflammatory demyelinating polyneuropathy (1 paper, 2012). "Elevated MMP-2 and MMP-9 immunoreactivity was found in nerve tissue in chronic inflammatory demyelinating polyneuropathy (CIDP) and nonsystemic vasculitic neuropathy (NSVN), compared to noninflammatory neuropathies (NINs)." (PMID 22970361, 2012).
chronic otitis media (1 paper, 2025). Chronic form of otitis media (disease). "In our study, we aimed to investigate the presence of MMP-2 and 9 in patients with chronic otitis media (COM) with tympanosclerosis and their possible effects on tympanosclerosis severity and prognosis." (PMID 40468054, 2025). "Our study provides direct evidence that both MMP-2 and MMP-9 are produced locally during tympanosclerosis and/or chronic otitis media." (PMID 40468054, 2025). "Our study provides direct evidence that both MMP-2 and MMP-9 are produced locally during the process of tympanosclerosis and/or chronic otitis media." (PMID 40468054, 2025).
chronic skin ulcers (1 paper, 2021). "It was found that the increase of MMP-2 in the exudate of chronic skin ulcers significantly affected the degradation of collagen and tissue destruction." (PMID 34211577, 2021).
clear-cell carcinoma (1 paper, 2016). "Only one patient with a clear-cell carcinoma had both epithelial and stromal MMP-14 and MMP-2 expression." (PMID 27038607, 2016). "A case of clear-cell carcinoma shows intense expression for MMP-14 (1c) and less intense expression for MMP-2 (1d)." (PMID 27038607, 2016). "In our cohort, MMP-14 and MMP-2 expression are not confined to clear-cell carcinomas, and not all clear-cell carcinomas express both proteins." (PMID 27038607, 2016). "Nor epithelial MMP-14 and MMP-2 expression, nor stromal MMP-14 and MMP-2 expression was related to stage or survival in these seven patients with a clear-cell carcinoma." (PMID 27038607, 2016).
cocaine abuse (1 paper, 2007). Disorders related or resulting from use of cocaine. "We examined whether the target molecules of RECK, MMP2 and MMP9 were regulated by cocaine abuse." (PMID 18000554, 2007).
colorectal tubulovillous adenoma (1 paper, 2021). A neoplasm that arises from the glandular epithelium of the colonic and rectal mucosa. "The levels of 20S proteasomes in exosomes, MMP9+, MMP9+/MMP2+/EMMPRIN+ in CD9-positive blood plasma exosomes are associated with the risk of malignant transformation of colorectal tubulovillous adenomas." (PMID 33773551, 2021).
congenital muscular dystrophy (1 paper, 2011). A muscular dystrophy that is characterized by diminished muscle tone (hypotonia), progressive muscle weakness and degeneration (atrophy), abnormally fixed joints, spinal rigidity, and delays in reaching motor milestones such as sitting or standing unassisted. "MMP-2 activity was found to be associated with the extent of pathological injury in mdx muscles, especially in the diaphragm and increased MMP-2 activity was demonstrated in a patient with congenital muscular dystrophy." (PMID 21445359, 2011).
conjunctivitis (1 paper, 2024). Inflammation of the conjunctiva of the eye. "In particular, MMP-2 and MMP-9 cause the disruption of corneal barrier with the digestion of mucins, resulting in an increase in corneal irregularity and permeability and conjunctivitis with the desquamation of the corneal epithelium." (PMID 38885258, 2024).
corneal disease (1 paper, 2022). "MSCs therapy in corneal disease inhibits infiltration of immune cells such as CD68+ macrophages and decreases pro-inflammatory cytokines, such as IL-2, IL-17, VEGF and matrix metallopeptidase 2 (MMP2)." (PMID 35422841, 2022).
craniopharyngioma (1 paper, 2024). A benign, partly cystic, epithelial tumor of the sellar region, presumably derived from Rathke pouch epithelium. "In a study of ACP in children, MMP-2 expression was higher in recurrent than in primary craniopharyngiomas." (PMID 38594611, 2024).
dacryoadenitis (1 paper, 2016). Inflammation and enlargement of the lacrimal gland. "In the current study, we found that ADSC treatment significantly downregulated the mRNA expression of MMP-2 and MMP-9 in the LGs of dacryoadenitis rabbits." (PMID 27699412, 2016). "Decreased production of MMP-2 and MMP-9 could lead to reduced leukocyte recruitment to the LGs, resulting in diminished inflammatory infiltrates in the LGs of dacryoadenitis rabbits treated with ADSCs." (PMID 27699412, 2016).